TSC1 (TSC complex subunit 1)
Diseases named in the same sentence as TSC1 in open-access papers (continued):
Sharing a sentence is not in itself a finding about the gene and the disease.
myopathy (6 papers, 2016 to 2023). A disease of the muscle in which the muscle fibers do not function properly. "TSC1 deficient mice, showing prolonged and chronic elevated mTORC1, developed late onset myopathy, showed vacuolated and basophilic fibers, intracellular inclusions, and abnormally large myonuclei." (PMID 31552262, 2019). "Furthermore, extracellular binding proteins were impaired in TSC1 deficient mice which may be an attenuating factor to myopathy." (PMID 31552262, 2019). "Here, we investigated the mechanisms underlying mTORC1-driven muscle atrophy in young, pre-myopathic TSCmKO mice and following acute TSC1 depletion in young mice, thereby avoiding influence from secondary consequences of the late-onset myopathy." (PMID 36302954, 2022). "It has been previously reported that sustained activation of mTORC1 inhibits autophagy and leads to late‐onset myopathy in a TSC1 null mouse model." (PMID 30924297, 2019). "Interestingly, sustained activation of mTORC1 by depletion of TSC1 (TSCmKO mice) also results in a late-onset myopathy." (PMID 27004103, 2016).
neurological disease (5 papers, 2012 to 2026). "Importantly, aberrant expression of TSC1 or TSC2 causes significant neurological disease, and overactivation of mTOR has been linked to the development of neurodegenerative disorders." (PMID 28732515, 2017). "Mutations in either of two tumor suppressor genes, TSC1 or TSC2, cause tuberous sclerosis complex (TSC), a syndrome resulting in benign hamartomatous tumors and neurological disorders." (PMID 23028662, 2012). "Herein, we investigate genotypic prediction from long-term EEG signals of freely behaving mice belonging to six groups defined by the presence or absence of a neurological disease-genotype (TSC1 gene knockout) in three different inbred strains with distinct genetic backgrounds." (PMID 40894539, 2025).
bacterial infection (4 papers, 2016 to 2022). "TSC1 deficiency impairs CD8+ T cell responses to bacterial infections." (PMID 36186130, 2022). "During bacterial infection, we found that the immune response is impaired in TSC1 KO mice, as evidenced by the greater numbers of bacteria in the blood, lower concentration of proinflammatory cytokines, and greater mortality in TSC1 KO mice." (PMID 27746591, 2016). "The TSC1/2 heterodimer, a key upstream regulator of the mTOR, can inhibit the activation of mTOR, which plays a critical role in immune responses after bacterial infections." (PMID 27746591, 2016). "Because Treg numbers increased and CD4+ effector T cells decreased, the immune response to bacterial infection seemed to be weakened in TSC1 KO mice." (PMID 27746591, 2016). "During bacterial infection, we found a greater number of bacteria in the blood, lower concentration of proinflammatory cytokines, and a higher mortality rate in TSC1 KO mice when compared to WT mice." (PMID 27746591, 2016). "To compare resistance to bacterial infection in WT and TSC1 KO mice, we infected WT and TSC1 KO mice with E. coli (5∗105 cells/mouse)." (PMID 27746591, 2016). "To investigate whether mTOR inhibitor, rapamycin, could alter bacterial-induced autophagy, we treated both TSC1 WT and KO BMMφ with rapamycin 1 h prior to bacterial infection with TB and BCG." (PMID 27387347, 2016). "During bacterial infection, the percentage and number of activated effector CD4+ T cells decreased in TSC1 KO mice." (PMID 27746591, 2016). "After examination of coactivators in monocytes after bacterial infection, we found reduced expression of coactivators (i.e., CD40, CD86, MHC-II, and CD14) from TSC1 KO mice and WT mice." (PMID 27746591, 2016). "However, some colleagues demonstrated that TSC1 deficiency did not change the proliferation of CD8+ T cells in vitro, but inhibited their proliferation in vivo in a bacterial infection model." (PMID 36186130, 2022).
adenocarcinoma (3 papers, 2014 to 2017). A common cancer characterized by the presence of malignant glandular cells. "Recently, Ding and co-workers reported that Tsc1 ablation mediated by Neurogenin 3-Cre (Neurog3Cre; Tsc1-/- mice) also induced “adenocarcinoma-like” lesions showing features of ACCs." (PMID 26683340, 2015). "Sequence alterations of TSC1 were found in only one cell line, i.e. the “HCC827” cells, i.e. an adenocarcinoma cell line harboring an acquired mutation within the EGFR tyrosine kinase domain." (PMID 24593867, 2014).
brain disorder (3 papers, 2013 to 2023). A disease affecting the brain or part of the brain. "In this study we have generated a new model of TSC brain disease by exogenous injection of Cre expressing AAV virus at birth to pups that are homozygous for the conditional allele of Tsc1, Tsc1c/c mice." (PMID 23696872, 2013). "A number of mouse models of TSC brain disease have been generated using conditional alleles of either Tsc1 or Tsc2, and a variety of Cre recombinase alleles driven by different brain-specific promoters, typically active during embryonic development, and in some cases drug-inducible." (PMID 23696872, 2013). "The Pten/Tsc1 deletion model faithfully recapitulates most aspects of SEGAs and provides one of the most compelling examples that rodents can be used to model human brain disorders." (PMID 38107199, 2023).
kidney disease (3 papers, 2020 to 2024). "Moreover, given the unusually strong family history of renal disease, this particular TSC1 mutation may have a strong propensity for kidney disease manifestation." (PMID 38802873, 2024). "With TSC1 and TSC2 patients combined, the prevalence of organ involvement stood at 70% of patients with a CHD, 88% with an NDD and 63% with renal disorders." (PMID 35440050, 2022).
kidney (2 papers, 2024 to 2025). "In our Tsc1 and Tsc2 mutant mice, liver and kidney tumors were observed at the age of 12-month-old." (PMID 41238564, 2025). "Adoptive transfer of AKT- or MST1-overexpressing macrophages, or Keap1 disruption in myeloid-specific TSC1-knockout mice promoted NRF2 activation but reduced TLR4 activity and mitigated I/R-induced liver inflammation." (PMID 38360839, 2024).
CNS tumors (1 paper, 2014). "Experimental approaches to identify the cell of origin in TSC have focused to date almost exclusively on validating the hypothesis that the CNS tumors and behavioral phenotypes are driven by TSC1 or TSC2 mutations in the NSC lineage." (PMID 25505789, 2014). "Few studies have directly investigated the hypothesis that TSC1 or TSC2 mutations in neural crest stem cells drive the development of non-CNS tumors in TSC, including LAM." (PMID 25505789, 2014).
endocrine tumors (1 paper, 2021). "There is no clear genotype-phenotype correlation, but patients with TSC2 mutations show more severe disease than those with TSC1 mutations, although it does not involve endocrine tumors." (PMID 34025587, 2021).
inflammation (1 paper, 2024). Aberrant reaction of the microcirculation characterized by movement of fluid and leukocytes from the blood into extravascular tissues. "Our findings underscore the critical role of macrophage TSC1 as a novel regulator of innate immunity and imply the therapeutic potential for the treatment of sterile liver inflammation in transplant recipients." (PMID 38360839, 2024).
neoplastic disorder (1 paper, 2020). "Loss of the TSC complex members hamartin (TSC1) or tuberin (TSC2), which drives constitutive mTORC1 activation, leads to the development of a multi-system low-grade tumor and neoplastic disorder called tuberous sclerosis." (PMID 32733892, 2020).
skeletal dysplasia (1 paper, 2017). Any Mendelian diseases that affects growth and development of the skeleton. "In this investigation, the mTORC1 inhibitor rapamycin partly rescued the skeletal dysplasia and corrected the spinal deformity of TSC-1-specific KO mice." (PMID 28523278, 2017).
TSC1 also shares sentences with these, for which no sentence is quoted: Rett syndrome (5 papers); Angelman syndrome (3); anxiety disorder (3); cystic lung disease (3); endometrial cancer (3); gastric cancer (3); metabolic disease (3); Peutz-Jeghers syndrome (3); tuberous sclerosis 1 (3); cardiac tumors (2); fibrosis (2); focal seizures (2); frontotemporal dementia (2); head and neck cancer (2); hematological disease (2); hemimegalencephaly (2); hypercholesterolaemia (2); Hyperinsulinemia (2); lupus (2); Macrocephaly (2); pancreatic (2); pulmonary lymphangioleiomyomatosis (2); schwannomatosis (2); acute leukemia (1); Adams-Oliver syndrome 5 (1); Aicardi syndrome (1); anaplastic oligoastrocytoma (1); Atrophy (1); autosomal dominant lateral temporal lobe epilepsy (1); band heterotopia (1).
A further 100 diseases each share a sentence with TSC1 in 1 paper.